RPA3 (replication protein A3)
Diseases named in the same sentence as RPA3 in open-access papers:
RPA3 is named in the same sentence as 39 diseases in open-access papers, as found by Europe PMC text mining. Sharing a sentence is not in itself a finding about the gene and the disease. The quoted sentences say what the papers report.
breast carcinoma (5 papers, 2019 to 2025). "In the whole cohort, low nuclear RPA3 protein was associated with poor breast cancer-specific survival (BCSS) (P = 0.005)." (PMID 36997566, 2023). "In ER + breast cancers that received endocrine therapy, low nuclear RPA3 protein was associated with poor BCSS (P < 0.0001)." (PMID 36997566, 2023). "In the whole cohort, low cytoplasmic RPA3 protein was associated with poor breast cancer-specific survival (BCSS) (P = 0.0004) and DMFS." (PMID 36997566, 2023). "The hazard ratio of other six genes (FAAP20, RRM2B, UBE2A,RAD50,MRE11, and RPA3) was >1, regarded as risk factors in developing breast cancer." (PMID 36713553, 2022). "Previous studies have shown that, in breast cancer, the analysis of eight DNA repair-related genes, including RPA3 and XRCC4, among others, reveals that patients exhibiting high expression levels of these genes tend to have poorer prognoses." (PMID 40243892, 2025). "In total, 11 DNA repair genes (UBE2A, RBBP8,RAD50, FAAP20, RPA3, ENDOV, DDB2, UBE2V2,MRE11, RRM2B, andPARP3) were preserved as prognostic genes to estimate risk score, which was applied to establish the prognostic model and stratified breast cancer patients into two groups with high or low risk." (PMID 36713553, 2022). "In order to prove the anti-tumor effect of Diazinon in BC, we used it to treat breast cancer cells and observed that it increased the expression of TAT while suppressing the expression of CDC6, RPA3, POLD1, and POLD2." (PMID 39334853, 2024). "A total of 11 DNA repair genes, namely, UBE2A, RBBP8,RAD50, FAAP20, RPA3, ENDOV, DDB2, UBE2V2,MRE11, RRM2B, andPARP3, were involved in the prognostic model for breast cancer patients." (PMID 36713553, 2022). "Low cytoplasmic RPA3 protein did not influence BCSS in TNBC or Her-2 positive breast cancers." (PMID 36997566, 2023). "Low cytoplasmic RPA3 protein was strongly associated with larger tumours, high grade, high stage, de-differentiation, high-risk Nottingham Prognostic Index (NPI), ER negative, PR negative, and luminal B breast cancers (all P values <0.001)." (PMID 36997566, 2023). "Low nuclear RPA3 protein did not influence survival in TNBC or Her-2 positive breast cancers." (PMID 36997566, 2023). "The expression level of DDB2, RPA3,RAD50, RRM2B, and UBE2A was higher in breast cancer tissues with lymph node metastasis compared with breast cancer tissues without lymph node metastasis, which was estimated by the distribution of their expression level between N0 and N1–N3 stages." (PMID 36713553, 2022).
brain tumors (3 papers, 2020 to 2023). "While most genes show elevated gene expression levels for all brain tumors, of interest is EXO1 and RPA3 which are only up-regulated in IDH-wt GBM samples." (PMID 36711972, 2023).
gastric cancer (3 papers, 2020 to 2022). A primary or metastatic malignant neoplasm involving the stomach. "All the three subunits RPA1, RPA2, and RPA3, were more abundant (with statistical significance evidence) in lymph node negative and earlier stage (stage I and II) gastric carcinomas." (PMID 36177351, 2022).
glioblastoma (3 papers, 2022 to 2026). The most malignant astrocytic tumor (WHO grade IV). "From the 84 DDR genes assessed, the high expression of ATP23, RAD51C and RPA3 was independently associated with poor OS outcomes in the TCGA IDH wild-type glioblastoma cohort." (PMID 35406779, 2022). "At the gene level, the high expression of ATP23, RAD51C and RPA3 independently associated with poor prognosis in glioblastoma patients." (PMID 35406779, 2022).
lung adenocarcinoma (3 papers, 2019 to 2024). A carcinoma that arises from the lung and is characterized by the presence of malignant glandular epithelial cells. "Replication protein A3 (RPA3) inhibited protective autophagy and promoted cisplatin resistance in lung adenocarcinoma." (PMID 37033959, 2023).
medulloblastoma (3 papers, 2023). A malignant, invasive embryonal neoplasm arising from the cerebellum. "Interestingly, 3 of the 5 medulloblastoma cases had novel and one very rare germline RPA1, as well as one ultra-rare RPA3 variant." (PMID 37869077, 2023). "For example, almost all the genes in the mismatch repair pathway have elevated gene expression levels in medulloblastoma, except EXO1, RPA3 and POLD4." (PMID 36918656, 2023).
colon cancer (2 papers, 2008 to 2017). "Genetic variations in DNA synthesis gene Rpa3 have been associated with susceptibility to carcinomas, whereas increased cancer expression of Rpa2 is associated with adverse outcome in colon cancer." (PMID 18706093, 2008).
glioma (2 papers, 2020 to 2025). A benign or malignant brain and spinal cord tumor that arises from glial cells (astrocytes, oligodendrocytes, ependymal cells). "The findings indicated that overexpression of RPA3 enhances the proliferation, migration, and invasion of glioma cells through the phosphorylation of PI3K, AKT, and mTOR, thereby activating the PI3K-AKT-mTOR signaling pathway." (PMID 40642071, 2025). "A recent study investigated the relationship between RPA3 and immune cell infiltration and activation by constructing a univariate Cox regression model to predict the prognosis of glioma patients." (PMID 40642071, 2025).
leukemia (2 papers, 2017 to 2020). A malignant (clonal) hematologic disorder, involving hematopoietic stem cells and characterized by the presence of primitive or atypical myeloid or lymphoid cells in the bone marrow and the blood. "We then verified the high knockout efficiency of our opAsCas12a system using crRNAs targeting essential gene Rpa3 and known leukemia dependency Brd419." (PMID 32661245, 2020). "While Rpa3 was required for proliferation of 4T1 cells in vitro, none of our lncRNAs showed depletion even after 14 days in culture, indicating that these lncRNAs are not required for general cell or tumor survival and growth, but rather are specifically required for leukemia maintenance." (PMID 28875933, 2017).
melanoma (2 papers, 2010 to 2025). A malignant, usually aggressive tumor composed of atypical, neoplastic melanocytes. "Functional assays on a subset of these candidates, including MET, ASPM, AKAP9, IMP3, PRKCA, RPA3, and SCAP2, validated their pro-invasion activities in human melanoma cells." (PMID 20520718, 2010). "To this end, we selected 6 genes from the candidate list (ASPM, AKAP9, IMP3, PRKCA, RPA3, and SKAP2) based on literature support (see Discussion) to determine whether their knockdown would impact on the invasion of a human melanoma cell, 1205LU." (PMID 20520718, 2010).
oligodendroglioma (2 papers, 2023). A well-differentiated (WHO grade II), diffusely infiltrating neuroglial tumor, typically located in the cerebral hemispheres. "We observe that different genes belonging to this pathway exhibit different trends, for example genes such as POLD1(chr19), RPA2(chr1), and LIG1(chr19) loose a copy in IDH-mut oligodendrogliomas, while genes RPA3(chr19), PMS2(chr19), PCNA(chr20) and POLD2(chr7) gain a copy in IDH-wt GBM." (PMID 36918656, 2023).
triple-negative breast carcinoma (2 papers, 2017 to 2023). An invasive breast carcinoma which is negative for expression of estrogen receptor (ER), progesterone receptor (PR), and human epidermal growth factor receptor 2 (HER2). "Consistent with our observations in the triple-negative breast cancer cells, guides targeting Rosa26 exhibited minimal dropout over five passages, while guides targeting RPA3 or PCNA were depleted up to 90-fold." (PMID 28337968, 2017).
anthrax (1 paper, 2022). "Results obtained in the current research enable the claim that modified anthrax antigens rPA1+2, rPA3+4 and rPA83m are resistant to degradation during extended storage under various temperature conditions and can serve as the basis for an anthrax vaccine." (PMID 35456639, 2022). "Thus, we consider the compositions of SPs with any one of modified anthrax antigen or with the combination of rPA1+2 and rPA3+4 as prospective anthrax vaccine candidates that are worthy of further study." (PMID 35456639, 2022). "Immunofluorescence analysis carried out to examine the state of the antigen adsorbed to SPs for 40 days demonstrated the maintenance of antigenic specificity of each of three anthrax antigens and the ability of rPA83m and rPA3+4 to interact with monoclonal PA-neutralising antibodies." (PMID 35456639, 2022). "Considering previously proven adjuvant properties and safety of SPs, their compositions with rPA83m/rPA1+2/rPA3+4 in any combinations might be suitable as a basis for new-generation anthrax vaccines." (PMID 35456639, 2022).
Eμ (1 paper, 2016). "Nevertheless, control shRNAs targeting essential genes (Rpa1, Rpa3 and Polr2b;) were consistently depleted in all four replicates, as were shRNAs targeting genes that either cooperated with Myc (Prmt5 and Odc) or belonged to known oncogenic pathways in Eμ-myc lymphomas (Adsl and Rsl24d1)." (PMID 27635472, 2016).
head and neck squamous cell carcinoma (1 paper, 2017). A squamous cell carcinoma that arises from any of the following anatomic sites: lip and oral cavity, nasal cavity, paranasal sinuses, pharynx, larynx, and salivary glands. "Moreover, TCGA data also indicated that high RPA3 expression correlated with poor OS and a high recurrence rate in patients with head and neck squamous cell carcinoma (HNSC) after radiotherapy." (PMID 28557284, 2017).
invasive breast carcinoma (1 paper, 2023). A carcinoma that infiltrates the breast parenchyma. "In invasive breast cancers, low nuclear RPA3 protein expression was observed in 53% (919/1747) of tumours." (PMID 36997566, 2023). "Whereas normal breast tissues have high levels of RPA1 expression, the nuclear RPA3 level was significantly reduced in DCIS and invasive breast cancers (P < 0.0001)." (PMID 36997566, 2023).
liver cancer (1 paper, 2020). An epithelial or non-epithelial malignant neoplasm that arises from the liver. "RPA3 is associated with the occurrence and poor prognosis of liver cancer, as well as the aging of hematopoietic stem cells." (PMID 33195193, 2020).
metastatic melanoma (1 paper, 2013). A melanoma that has spread from its primary site to another anatomic site. "Replication protein A3 gene (RPA3) was recently shown to be gained in metastatic melanoma (within an FMCR) and to play an essential role in tumour invasion." (PMID 24367615, 2013).
myelodysplastic syndrome (1 paper, 2023). A clonal hematopoietic disorder characterized by dysplasia and ineffective hematopoiesis in one or more of the hematopoietic cell lines. "Because germline RPA1 mutations are linked to early onset TBD with predisposition to myelodysplastic syndromes, we interrogated pediatric cancer cohorts to define the prevalence and spectrum of rare/novel and putative damaging germline RPA1, RPA2, and RPA3 variants." (PMID 37869077, 2023).
thromboangiitis obliterans (1 paper, 2022). A rare inflammatory non-necrotizing vascular disease affecting the small- and medium-sized arteries and veins of the upper and lower extremities characterized by endarteritis and vaso-occlusion due to occlusive thrombus development. "Although it is not specific for LEAD, a case-control GWAS of 177 patients with thromboangiitis obliterans (TAO) identified three SNPs (rs376511 in the IL17RC gene, rs7632505 in the SEMA5B gene, and rs10178082 in the RPA3 gene) that were significantly associated with TAO in the Uighur population." (PMID 36142394, 2022).
thyroid cancer (1 paper, 2024). "NHEJ- (XRCC6, XRCC5, PRKDC) and HR‐ (SSBP1, SEM1, RPA2, RPA3)-related genes were found to be expressed in both normal follicular and thyroid cancer cells." (PMID 38380364, 2024). "NHEJ- (XRCC6, XRCC5, PRKDC) and HR- (SSBP1, SEM1, RPA2, RPA3) related genes are expressed by both normal follicular and thyroid cancer cells." (PMID 38380364, 2024).
tumor (15 papers, 2010 to 2026). "Single-cell analysis suggested greater transcriptomic and network-level relevance of RPA3 in chr7-gain tumor cells." (PMID 42193341, 2026). "Further investigations revealed that knockdown of the TFs candidates—DDB1, PARP1, XRCC5, RPA1, and RPA3—resulted in a significant reduction in tumor sphere formation." (PMID 40230524, 2025). "Strikingly in organoids derived from two different tumours, after treatment with Shield-1 this fraction decreased to <20% for the RPA3-targeting sgRNA." (PMID 28224990, 2017). "We observed a drastic decrease in tumour growth in tumours expressing RPA3 sgRNA on Shield-1 treatment." (PMID 28224990, 2017). "Immuno-staining confirmed decreased RPA3 protein expression in tumour cells infected with RPA3 sgRNA on Shield-1 treatment." (PMID 28224990, 2017). "Low cytoplasmic RPA3 protein expression was observed in 55% (965/1747) of tumours." (PMID 36997566, 2023). "Thus, RPA2 and RPA3 could be considered as genes of unknown significance (GUS) yet potentially important in tumor formation." (PMID 37869077, 2023). "We observed a significant association between OS and the expression of six genes (CCNH, MLH3, RAD51C, RPA3, SLK, and XPA) in primary tumor tissues." (PMID 37240218, 2023). "In addition, we analysed the gene expression data of HNSC cases in the TCGA data set, which suggested that RPA1 and RPA3 were up‐regulated in HNSC tissues compared with non‐tumour tissues, whereas RPA2 expression did not significantly differ between HNSC and non‐tumour tissues." (PMID 28557284, 2017).
cancer (13 papers, 2008 to 2026). A tumor composed of atypical neoplastic, often pleomorphic cells that invade other tissues. "Within the pan-cancer cohort, we identified 80 cases with 55 germline heterozygous RPA1, RPA2 or RPA3 variants meeting criteria of AF < 0.5% in gnomAD non-cancer cohort and CADD score > 15 for candidate variant selection." (PMID 37869077, 2023). "To address this knowledge gap, we investigated the occurrence of novel and rare germline variants in RPA1, RPA2 and RPA3 genes, in a cohort of 5,993 children with cancers." (PMID 37869077, 2023). "By mining the Catalogue Of Somatic Mutations In Cancer (COSMIC) database, we found that somatic mutations in RPA1, RPA2, RPA3 are found in 1.4%, 0.5%, and 0.9% of human cancers, respectively." (PMID 37869077, 2023). "Based on these data, we reasoned that germline defects in RPA1 and possibly also the other 2 components of the RPA heterotrimer (RPA2 and RPA3) might be associated with cancer development." (PMID 37869077, 2023). "Maintaining the polyclonal nature of the resistant population, we first engineered HCC827-OsiR cells to stably express Cas9, which was functionally validated by targeting the pan-cancer essential gene RPA3." (PMID 40414926, 2025). "And additional research is required to clarify the regulatory relationships and underlying mechanisms of SSBP1, RPA3 and TUBB2A in Cancer cell lactylation despite demonstrating an association between them." (PMID 40642071, 2025). "RPA3 expression has been shown to correlate with poor prognosis and radioresistance in various cancers." (PMID 36281462, 2022). "The RPA (human replication protein A) family, including RPA1, RPA2, and RPA3, plays an essential role in eukaryotic DNA replication, homologous recombination, and excision repair; it has been recognized as an oncogene and therapeutic target for cancer." (PMID 37091868, 2023). "Furthermore, functional experiments demonstrated that RPA3 knockdown suppressed cancer cell proliferation and migration, sensitized cells to cisplatin treatment, and reduced global lactylation, which may serve as a novel biomarker and potential therapeutic target." (PMID 42196471, 2026). "We divided cancer cells into six groups: SSBP1+ cancer group, SSBP1− cancer group, RPA3+ cancer group and RPA3− cancer group, TUBB2A+ cancer group and TUBB2A− cancer group." (PMID 40642071, 2025). "The proportion of SSBP1, RPA3, and TUBB2A cancer cells increased synchronously during the quasi-time course." (PMID 40642071, 2025). "We also spiked in a panel of 41 negative control sgRNAs (targeting nonhuman genes such as Luc, LacZ, Ren and Rosa26 and scrambled sequences) and 27 positive control sgRNAs (targeting cancer-essential genes such as MYC, PCNA and RPA3)." (PMID 38316881, 2024). "Compared with Genome Aggregation Database (gnomAD) non-cancer controls, there was significant enrichment of ultra-rare and novel RPA1, but not RPA2 or RPA3, germline variants in our cohort (adjusted p-value < 0.05)." (PMID 37869077, 2023).
CNS tumors (1 paper, 2023). "Statistical analysis using two- and one-sided Fisher exact tests of ultra-rare plus novel and rare germline heterozygous variants in RPA1, RPA2 and RPA3 across hematologic, extra-cranial solid and CNS tumors." (PMID 37869077, 2023).
hematological malignancies (1 paper, 2023). "Germline heterozygous variants found in RPA1, RPA2 and RPA3 in pediatric hematological malignancies." (PMID 37869077, 2023). "Besides these descriptions associating germline RPA1 variants with bone marrow failure or hematologic malignancies, the RPA2 or RPA3 genes have not been linked to any human diseases thus far." (PMID 37869077, 2023).
RPA3 also shares sentences with these, for which no sentence is quoted: hepatocellular carcinoma (2 papers); colorectal cancer (1); Hodgkins lymphoma (1); interstitial lung disease (1); lung squamous cell carcinoma (1); lymph node metastasis (1); lymphoma (1); nasopharyngeal carcinoma (1); pancreatic cancer (1); premature ovarian failure (1); rheumatoid arthritis (1); sarcoma (1); spinocerebellar ataxia type 1 (1); Wilms tumor (1).